CENPE (centromere protein E)
Diseases named in the same sentence as CENPE in open-access papers (continued):
Sharing a sentence is not in itself a finding about the gene and the disease.
cancer (53 papers, 2008 to 2025). A tumor composed of atypical neoplastic, often pleomorphic cells that invade other tissues. "CENPE is also associated with various cancer types, and multiple CENPE inhibitors have been developed as potential cancer therapeutics." (PMID 37479754, 2023). "CENPE is also associated with various cancer types, and its loss results in cell division defects and cell death." (PMID 37479754, 2023). "We report widespread and consistent changes in alternative splicing of cancer-associated genes including CENPE, ESCO2, CKAP2, MELK, ASPH and CD164 in both HeLa and PC3 cells." (PMID 33846420, 2021). "CENPE is a microtubule motility protein that is implicated in oncogenesis of various kinds of cancer." (PMID 34868981, 2021). "CENPE has been associated to tumorigenesis in various types of cancer although few studies have been conducted in brain tumors." (PMID 33804489, 2021). "Among them, the CENPE gene encodes a centromere binding protein and mitotic kinesin, which has been demonstrated as a promising target for cancer drug development." (PMID 34745136, 2021). "CENPE is a motor protein, and its abnormal expression has been associated with various cancers." (PMID 40794013, 2025). "CENPE inhibitors disrupt mitotic spindle assembly, selectively targeting rapidly dividing cancer cells." (PMID 40794013, 2025). "As well as our findings, a large body of evidence indicated that CENPE is up‐regulated in a variety of cancers and exerts a cancer‐promoting function." (PMID 40794013, 2025). "Accordingly, CENPE loss of function increases chromosome misalignment, mitotic arrest, aberrant spindle positioning, CIN, and mitotic catastrophe in cancer, fibroblast, and liver regeneration models." (PMID 40002279, 2025). "The results of trials evaluating Eg5 and CENPE inhibitors in cancer patients indicate that they are ineffective as monotherapies." (PMID 40002279, 2025). "Both MPS1 and CENPE have been reported to be overexpressed in cancer cells, making them potential targets for cancer therapy." (PMID 38258067, 2023). "Several CENPE inhibitors have been developed for cancer treatment, including GSK923295, which is currently being studied in a phase I clinical trial of adult patients with solid tumors that have not responded to common therapies." (PMID 37479754, 2023). "Within these genes, AKAP9, CENPE, PRKCI, RDX, RECQL, and USO1 have also been reported to be associated with cancer progression." (PMID 31426369, 2019). "Previous studies suggested that CENPE acts as a tumor suppressor gene or oncogene in various cancers." (PMID 26933822, 2016). "Many studies have shown that CENPE acts as an oncogene in some cancers." (PMID 38702677, 2024). "Hence, high CENPE expression inhibits cell division, which leads to a better prognosis in cancer patients." (PMID 35496042, 2022). "However, like many anti-mitotic drugs, CENPE inhibitors have had limited clinical efficacy as monotherapies, which may be attributable to “mitotic slippage” of cancer cells that experience prolonged mitotic arrest in response to such drugs." (PMID 40002279, 2025). "CENPE expression might be induced under a stressful environment in cancer cells." (PMID 30716092, 2019). "Preclinical work demonstrating greater efficacy of CENPE, Eg5, and KIF18A inhibitors in aneuploid, tetraploid, and CIN-positive cancer models supports this concept." (PMID 40002279, 2025). "Other known and possibly yet undiscovered cancer mechanisms are captured by the SKY92, including cell cycle pathways (BIRC5, TOP2A, and CENPE), cell growth and proliferation (FGFR3), DNA repair (FANCF, FANCI, POLQ), and transcription factor (STAT1)." (PMID 34448362, 2022). "To consolidate CENPE as a target for MB treatment, we tested GSK923295, an allosteric inhibitor already in clinical trial for other cancer types." (PMID 33804489, 2021).
cancer (continued). "Within community 2, we also identified increased expression of regulators of cell proliferation (CENPE, MKI67, TOP2A, UBE2C, guanine), cancer, and pluripotency (DNMT3B, DPPA4, MYC, POU5F1, CRABP2)." (PMID 33771987, 2021). "To consolidate CENPE as a target for MB treatment, we tested GSK923295, a specific inhibitor already in clinical trials for other cancer types." (PMID 33804489, 2021). "We found that the hub genes (BUB1B, CDC25C, CENPE, kinesin and CCNB1) make up an essential response across many cancer types." (PMID 31396397, 2019). "CENPE and LDHA were identified as the important prognostic biomarkers in KICH, and they might be involved in the proliferation of cancer cell." (PMID 37925501, 2023). "Notably, as co-expressed genes, TOP2A, BUB1 and CENPE also interacted with the CENPF protein, the high expression of which predicted poor prognosis in cancers." (PMID 37108172, 2023). "However, it seems to be against the function of CENPE as a carcinogenic factor, because the CD8 + T cell and macrophage could inhibit the development of cancer." (PMID 37925501, 2023). "Gene expression analysis showed that clonogenic side population cells in cancers express genes involved in the cell cycle and mitosis (e.g., SKA1, CCNB1, CDC25C, CDC2, BIRC5, CENPE, AURKB, KIFs, TOP2A, ASPM) more strongly than non-side population cells." (PMID 23962337, 2013).
infection (2 papers, 2014 to 2024). The state of being infected such as from the introduction of a foreign agent such as serum, vaccine, antigenic substance or organism. "When PPP2R2A- and CENPE -depleted cells were infected with HPV16-GFP, infection was increased, which supported the notion that the length of NE absence may be a kinetic bottleneck for import of the vDNA during mitosis." (PMID 24874089, 2014).
CENPE also shares sentences with these, for which no sentence is quoted: breast tumors (4 papers); cervical cancer (3); medulloblastoma (3); microcephalic primordial dwarfism (3); pancreatic cancer (3); acute myeloid leukemia (2); colorectal cancer (2); melanoma (2); peripheral neuropathy (2); skeletal dysplasia (2); adenocarcinoma (1); aneuploidy (1); autosomal recessive primary microcephaly (1); breast invasive carcinoma (1); chromophobe renal cell carcinoma (1); colon adenocarcinoma (1); colorectal adenocarcinoma (1); esophageal squamous cell carcinoma (1); essential hypertension (1); genetic diseases (1); head and neck squamous cell carcinoma (1); hyperglycaemia (1); hypopharyngeal cancer (1); invasive ductal carcinoma (1); lung adenoma (1); lung squamous cell carcinoma (1); metastatic disease (1); migraine (1); neurodegenerative disease (1); rectal adenocarcinoma (1).
A further 7 diseases each share a sentence with CENPE in 1 paper.